CELA3B (chymotrypsin like elastase 3B)
Description:
Efficient protease with alanine specificity but only little elastolytic activity.
Synonyms: ELA3B; CBPP
Tractability: Antibody: UniProt predicts a signal peptide or a membrane-spanning region.
Gene: Protein-coding gene on chromosome 1 (21,977,022 to 21,998,642, forward strand). Ensembl gene ENSG00000219073.
Subcellular location (Human Protein Atlas): Cytosol; Predicted to be secreted
Pathways (Reactome):
Developmental Biology: Developmental Lineage of Pancreatic Acinar Cells
Gene Ontology:
Molecular function: peptidase activity; serine-type endopeptidase activity
Biological process: proteolysis
Genetic constraint (gnomAD): Loss-of-function variants: 34 observed, 35.37 expected, observed/expected ratio (o/e) 0.96, 90% interval 0.73 to 1.28. The upper end of that interval is the gene's LOEUF score, 1.28, which puts it in group 5 of 6, group 1 being the genes least tolerant of losing a copy. Missense variants: 339 observed, 348.46 expected, observed/expected ratio (o/e) 0.97, 90% interval 0.89 to 1.06. Synonymous variants: 124 observed, 137.14 expected, observed/expected ratio (o/e) 0.9, 90% interval 0.78 to 1.05.
Homologues: Orthologues: chimpanzee CELA3B (99% identical), macaque CELA3B (94% identical), dog CELA3B (85% identical), mouse Cela3b (84% identical), rat Cela3b (81% identical), mouse Cela3a (77% identical), tropical clawed frog cela3a (63% identical). Paralogues in human: CELA3A (93% identical), CELA2A (58% identical), CELA2B (54% identical), CELA1 (50% identical), ELANE (34% identical), PRTN3 (33% identical).
Diseases named in the same sentence as CELA3B in open-access papers:
CELA3B is named in the same sentence as 20 diseases in open-access papers, as found by Europe PMC text mining. Sharing a sentence is not in itself a finding about the gene and the disease. The quoted sentences say what the papers report.
pancreatic cancer (5 papers, 2008 to 2023). "Among 17 different cancer categories (n = 7,932 samples), significant CELA3B expression was only found in 144 of 176 (82%) analyzed pancreatic cancers." (PMID 37379306, 2023). "The 5 CELA3B positive non-pancreatic cancers included several salivary gland tumors with weak to moderate cytoplasmatic granular staining." (PMID 37379306, 2023). "That CELA3B immunostaining was only weak in a fraction of our acinar cell carcinomas is consistent with earlier data describing a reduced CELA3B expression in pancreatic cancer cell lines and tissues as compared to adjacent pancreatic normal tissues." (PMID 37379306, 2023). "Based on our data, it can be assumed that these CELA3B positive cases include acinar cell carcinomas and other pancreatic neoplasms of which the analyzed samples also contained normal pancreatic tissue." (PMID 37379306, 2023). "Given the unequivocal CELA3B staining in normal epithelial cells from excretory ducts and the previous observation of CELA3B upregulation in pancreatic intraepithelial neoplasia and pancreatic carcinomas of rats this finding was not expected." (PMID 37379306, 2023).
pancreatitis (3 papers, 2008 to 2025). Inflammation of the pancreas. "A loss-of-function variant in CELA3B is associated with non-alcoholic CP, indicating that reduced CELA3B function predisposes one to pancreatitis." (PMID 40004893, 2025).
chronic pancreatitis (2 papers, 2016 to 2019). A chronic inflammatory process causing damage and fibrosis of the pancreatic parenchyma. "Variant c.643-7G>T in CELA3B showed an association with alcoholic chronic pancreatitis with a small protective effect (OR = 0.59, 95% CI = 0.39–0.89, p = 0.01)." (PMID 27999401, 2016). "Since position 241 is polymorphic both in CELA3A (p.G241A) and CELA3B (p.A241G), genetic analysis can directly assess whether individual variability in complex formation might alter risk for chronic pancreatitis." (PMID 27999401, 2016). "Here we sequenced exon 7 of CELA3A and CELA3B in a cohort of 225 subjects with chronic pancreatitis (120 alcoholic and 105 non-alcoholic) and 300 controls of Hungarian origin." (PMID 27999401, 2016).
acinar cell carcinoma (1 paper, 2023). "Our data show a good sensitivity (75%) and a high specificity (99.9%) of CELA3B immunohistochemistry for diagnosing acinar cell carcinoma of the pancreas." (PMID 37379306, 2023). "This interaction fits well with the significant association of CELA3B and CPA1 expression in acinar cell carcinomas." (PMID 37379306, 2023). "Given its high specificity, CELA3B immunohiostochemistry may represent a useful tool for supporting the difficult diagnosis of acinar cell carcinoma, although the positivity rate was only 75%." (PMID 37379306, 2023). "Reduced CELA3B (and CPA1) expression in acinar cell carcinomas may reflect cellular de-differentiation and could therefore potentially be linked to unfavorable patient prognosis." (PMID 37379306, 2023).
acinar cell carcinoma of the pancreas (1 paper, 2023). "The successful analysis of 13,223 cancers from 132 different tumor entities revealed that CELA3B expression was strikingly linked to acinar cell carcinoma of the pancreas (12 of 16 cases positive)." (PMID 37379306, 2023). "The extent of CELA3B immunostaining was significantly linked to the level of CPA1 expression in 16 pancreatic acinar cell cancers (p<0.0001) for which data were available from an earlier study." (PMID 37379306, 2023). "As a part of an antibody panel, CELA3B immunohistochemistry may represent a useful diagnostic marker for confirming the difficult diagnosis of pancreatic acinar cell carcinoma." (PMID 37379306, 2023). "A cytoplasmatic CELA3B positivity was most commonly seen in acinar cell carcinoma of the pancreas (75% of 16 spots positive, 37% strongly positive)." (PMID 37379306, 2023). "Among tumors, CELA3B immunostaining was seen in 12 of 16 (75%) acinar cell carcinoma of the pancreas including 6 cases with strong staining (37.5%) as well as in 5 of 13,207 other tumors (0.04%)." (PMID 37379306, 2023). "Unequivocal CELA3B positivity was not seen in tumors other than pancreatic acinar cell carcinomas in this study." (PMID 37379306, 2023).
cyst (1 paper, 2023). A sac-like closed membranous structure that may be empty or contain fluid or amorphous material. "N-glycosylated CELA3B (Asn-114, H5N4F1S0) and ATP6V0A1 (Asn-273, H5N4F0S1) were discarded from cyst fluid biomarkers due to their poor discriminative ability shown by PRM analysis." (PMID 37848412, 2023).
pancreatic disease (1 paper, 2016). "To this end, in the present paper we compared allele frequencies of variants p.G241A in CELA3A and p.A241G in CELA3B between subjects with CP and controls without pancreatic disease." (PMID 27999401, 2016). "To investigate whether changes in complex formation between human procarboxypeptidases and proelastases alter risk for CP, we investigated the frequency of variants c.722G>C (p.G241A) in CELA3A and c.722C>G (p.A241G) in CELA3B in subjects with CP and controls without pancreatic disease." (PMID 27999401, 2016).
salivary gland tumors (1 paper, 2023). "It is quite possible that the pathological activation of CELA3B in some salivary gland tumors is another expression of similarities between the two organs." (PMID 37379306, 2023).
cancer (2 papers, 2022 to 2023). A tumor composed of atypical neoplastic, often pleomorphic cells that invade other tissues. "A role of CELA3B in cancer has recently been proposed due to results from genome- and transcriptome-wide association studies as well as large-scale next generation sequencing studies." (PMID 37379306, 2023). "Moreover, pan-cancer RNA expression data available from the cBioPortal for cancer genomics suggest that CELA3B can be occasionally expressed also in other tumor types." (PMID 37379306, 2023). "CELA3B immunostaining was completely absent in a further 13,202 evaluable tumors from 128 different cancer types and subtypes." (PMID 37379306, 2023).
tumor (2 papers, 2023). "CELA3B expression was successfully analyzed in 13,223 tumor samples from 132 different tumor types and subtypes as well as 8 samples each of 76 different normal tissue types by immunohistochemistry in a tissue microarray format (TMA)." (PMID 37379306, 2023). "A CELA3B immunostaining was observed in 17 of 13,223 successfully analyzed tumors which all belonged to only 4 of 132 analyzed tumor categories." (PMID 37379306, 2023).
CELA3B also shares sentences with these, for which no sentence is quoted: diabetes (2 papers); Pancreatic Insufficiency (2); brain tumours (1); ductal adenocarcinoma (1); ductal adenocarcinoma of the pancreas (1); malignant brain tumors (1); Obesity Syndrome (1); Pancreatic cysts (1); prostate carcinoma (1); pulmonary disease (1).